SNORA63C (small nucleolar RNA, H/ACA box 63C)
Gene: Small nucleolar RNA gene on chromosome 1 (36,418,450 to 36,418,578, reverse strand). Ensembl gene ENSG00000201448.
Gene Ontology:
Biological process: RNA processing
Cellular component: nucleolus
Homologues: Orthologues: chimpanzee SNORA63 (98% identical), macaque SNORA63 (94% identical), rabbit SNORA63 (88% identical), dog SNORA63 (84% identical), mouse Gm55296 (69% identical). Paralogues in human: SNORA63 (92% identical), SNORA63 (91% identical), SNORA63E (78% identical), SNORA63D (74% identical), SNORA63B (64% identical), SNORA63 (61% identical), SNORA63 (60% identical), SNORA63 (58% identical), SNORA63 (49% identical).